NLRP3 (NLR family pyrin domain containing 3)
Diseases named in the same sentence as NLRP3 in open-access papers (continued):
Sharing a sentence is not in itself a finding about the gene and the disease.
infarction (26 papers, 2017 to 2025). A localised pathological necrosis of tissue resulting from obstruction of the blood supply usually by a thrombus, an embolus, or vascular torsion. "Firstly, macrophage polarization dynamics (especially NLRP3 inflammasome-driven M1 activation and therapeutic M2 polarization) have emerged as key regulators of post-infarction remodeling, with clinical trials demonstrating the efficacy of IL-1β inhibition." (PMID 40587711, 2025). "They found that the NLRP3 inflammasome inhibitor MCC950 significantly reduced cerebral infarct volume, inhibited caspase-1 activation, attenuated inflammation, and stabilized the blood-brain barrier, thereby preventing I/R injury." (PMID 40606597, 2025). "In this study, POSTN‐driven p16 deletion was found to enhance cardiac function and attenuate post‐infarction ventricular remodelling in MI mice, accompanied by suppressed myocardial inflammation and NLRP3 signalling activation." (PMID 40462499, 2025). "M2‐Exosome promoted miR‐148a expression thus ameliorated myocardial pyroptosis, cardiac injuries, myocardial Ca2+ overload and infarction through TXNIP/TLR4/MyD88/NF‐κB/NLRP3 signalling pathway in I/R rats." (PMID 39929748, 2025). "Mechanistically, colchicine was found to reduce the release of pro-inflammatory factors and the activation of NLRP3 inflammasome in the infarcted myocardium of mice 24 h after infarction." (PMID 38172692, 2024). "In the ex vivo Langendorff model, NLRP3 inflammasome was upgraded in myocardial fibroblasts, NLRP3-/- mice had smaller areas of infarction." (PMID 36204568, 2022). "Melatonin treatment attenuated inflammatory response by inhibiting the reactive oxygen species (ROS) and NLRP3 inflammasome, alleviating neuronal injury, and reducing infarction and hematoma volume, finally improving neurological score." (PMID 33777317, 2021). "After MI surgery, massive amounts of NLRP3 were accumulated in the infarction area, whereas a small amount of NLRP3 was scattered in the border zone area." (PMID 32908628, 2020). "Treatment with RSV significantly decreased the accumulation of NLRP3 both in the infarction area and border zone." (PMID 32908628, 2020). "Likewise, sacubitril/valsartan (LCZ696), an angiotensin receptor neprilysin inhibitor (ARNI), demonstrated notable suppression of NLRP3‐mediated pyroptosis, leading to reduced infarction and improved cardiac function in AMI rats." (PMID 39929748, 2025). "Caspase-1 is a critical component of the NLRP3 inflammasome that regulates cardiac remodeling post-infarction, whereas its role in rejection is unknown." (PMID 37781362, 2023). "NLRP3 inflammasome is a significant contributor to infarction size during the I/R process." (PMID 36204568, 2022). "Pretreatment with Nicorandil improved cardiac functions, infarction, and inflammation by inhibiting TLR4/MyD88/NF‐κB/NLRP3 signalling pathway thus reduced myocardial pyroptosis in rats with AMI." (PMID 39929748, 2025). "Results showed that AM-SB significantly reduced infarction volume, inflammation (IL-1β, TNF-α), and pyroptosis-related markers (NLRP3, GSDMD, ASC, Caspase-1), while decreasing gliosis and improving cerebral metabolites." (PMID 39859214, 2025). "By scavenging reactive oxygen species, modulating toll-like receptor signaling, and suppressing NLRP3 inflammasome activation, HDL-3 dampens post-infarction sterile inflammation and ventricular remodeling independent of plaque burden." (PMID 41586214, 2025). "HSYA effectively suppressed NLRP3 inflammasome activation in rats with MIRI, resulting in decreased IL-1β release and infarction size." (PMID 40271057, 2025). "Myocardial fibroblasts in the ex vivo Langendorff model presented an increase in the NLRP3 inflammasome, and mice lacking NLRP3 presented smaller infarction areas." (PMID 40079000, 2025).
allergic asthma (25 papers, 2014 to 2025). A asthma with a basis in a pathological type I hypersensitivity reaction. "To date, the key players and underlying mechanisms in the interaction between NLRP3 and epithelial barrier integrity in type 2-mediated allergic asthma are poorly understood." (PMID 41394833, 2025). "More recently, emerging evidence suggests that NLRP3 deficiency or deficiency of critical components of the NLRP3 inflammasome may promote the development of allergic asthma." (PMID 41394833, 2025). "Our previous study found that TLRs on peritoneal macrophage promotes the allergic asthma by maintaining the NLRP3/IL-1β signaling, but in this study, activation of TLRs signaling in sensitization-recruited monocytes could attenuate allergic asthma by producing Th1-associated cytokines." (PMID 30510553, 2018). "In summary, our findings highlight a protective role of NLRP3 in maintaining the local airway epithelial barrier and controlling airway hyperreactivity and mucus hypersecretion in a Th2-mediated allergic asthma model." (PMID 41394833, 2025). "Our study aims to evaluate the protective mechanisms of NLRP3 on airway epithelium and its structural and functional components during type 2-mediated allergic asthma inflammation." (PMID 41394833, 2025). "NLRP3 is essential for epithelial barrier integrity in the lung and protects from the development of allergic asthma in a murine model." (PMID 41394833, 2025). "Studies have shown that RRx-001 significantly inhibits HDM-induced eosinophil, neutrophil, and lymphocyte infiltration of the airways and improves allergic asthma symptoms by inhibiting NLRP3 activation and eosinophilic airway inflammation." (PMID 39131161, 2024). "Natural medical plants are also playing a therapeutic role in the pathological processes of NLRP3-mediated allergic asthma." (PMID 39131161, 2024). "HDM activates airway epithelial cells via Toll-like receptor (TLR), leading to NF-κB activation and secretion of pro-inflammatory cytokines, such as IL-6 and IL-1β, and also activates NLRP3 to promote HDM-induced inflammatory response in allergic asthma." (PMID 39364406, 2024). "Nevertheless, further research is required to decipher the exact role of NLRP3 inflammasome in the pathomechanism of allergic asthma." (PMID 36203607, 2022). "There is ample evidence that the activation of NLRP3 inflammasome acts directly on the development of allergic asthma." (PMID 36203607, 2022). "Previous studies have shown that the NLRP3 inflammasome is also involved in the pathogenesis of allergic asthma." (PMID 36033385, 2022). "The review presented, discusses the contribution of NLRP3 inflammasome to the development of allergic rhinitis, allergic asthma, and COPD." (PMID 36203607, 2022). "Inhibition of the inflammasome activity of NLRP3 can reduce airway inflammatory cell infiltration and mucus secretion in allergic asthma." (PMID 36033385, 2022). "Studies have demonstrated that NLRP3 inflammasome activation is involved in the allergen-driven airway inflammatory responses in mouse models of allergic asthma." (PMID 36248872, 2022). "Some research suggests that NLRP3 in bronchial epithelial cells or TH2 cells promotes the inflammatory response in allergic asthma." (PMID 34413860, 2021). "Our results indicate that the NLRP3-specific inhibitor RRx-001 exerts beneficial effects on allergic asthma." (PMID 34413860, 2021). "Our results showed that NLRP3 in myeloid cells promoted the development and progression of allergic asthma in an inflammasome-dependent manner." (PMID 34413860, 2021). "Excessive nucleotide-binding oligomerization domain-like receptor family, pyrin domain-containing 3 (NLRP3) inflammasome and concomitant IL-1β responses play a critical role in steroid-resistant SA and promote Th17 allergic asthma in mice." (PMID 34777398, 2021).
allergic asthma (continued). "In this study, to evaluate the relationship between mitochondrial reactive oxygen species (ROS) and NLRP3 inflammasome activation in allergic asthma, we used a newly developed mitochondrial ROS inhibitor, NecroX-5." (PMID 25356867, 2014). "In line with the concept of metabolic intervention, alanyl-glutamine has been reported to reshape the gut microbiota, increase butyrate, activate AMP-activated protein kinase (AMPK) signaling, and inhibit the NLRP3 inflammasome, thereby alleviating inflammatory pathology in allergic asthma." (PMID 41395465, 2025). "This study aimed to investigate the role of GLCCI1 in the regulation of nucleotide-binding oligomerization domain (NOD)-like receptor (NLR) family pyrin domain-containing 3 (NLRP3) by the phosphatidylinositol 3-kinase (PI3K) pathway in the pathogenesis of allergic asthma." (PMID 39834584, 2024). "Furthermore, the involvement of the NLRP3 inflammasome in the development and exacerbation of allergic asthma has been demonstrated." (PMID 39131161, 2024). "To summarise, the activity of the NLRP3 inflammasome seems to play a crucial role in the development of inflammation-based respiratory disorders such as allergic rhinitis allergic asthma, and COPD, and significantly exacerbates the development of these diseases." (PMID 36203607, 2022). "In animal models, NLRP3 inflammasome has also been confirmed to play a key role in allergic asthma." (PMID 36248872, 2022). "Moreover, NLRP3 inflammasome-specific inhibitors can significantly prevent respiratory inflammation and airway hyperresponsiveness in a mouse model of severe allergic asthma." (PMID 35500231, 2022). "Furthermore, the role of NLRP3 inflammasome was confirmed in the development of allergic asthma induced by house dust mite (HDM)." (PMID 36203607, 2022). "NLRP3 also promotes the inflammatory response in allergic asthma." (PMID 34413860, 2021). "In addition to powerful anti-inflammatory effects, dexamethasone has been reported to suppress the NF-κB/NLRP3 pathway in ovalbumin-induced allergic asthma." (PMID 34512868, 2021). "Nlrp3-/- mice were resistant to lung inflammation in HDM-induced allergic asthma." (PMID 34413860, 2021). "Next, we used HDM to induce allergic asthma in Nlrp3-/- mice and wild-type mice." (PMID 34413860, 2021). "Collectively, the specific roles of NLRP1 and NLRP3 in allergic asthma are still unclear." (PMID 33546184, 2021). "Furthermore, a recent report has shown that Saa3 activates the NLRP3 inflammasome and promotes Th17 allergic asthma in mice." (PMID 27929048, 2016). "However, the specific role of NLRP3 in allergic asthma remains controversial." (PMID 38933263, 2024). "Chrysanthemum improved the OVA-induced allergic asthma by inhibiting the activation of pro-inflammatory cytokines and their upstream TLR/NF-κB/NLRP3 pathways." (PMID 35911120, 2022). "Our study demonstrates NLRP3 as an important regulator in eosinophilic allergic asthma and that RRx-001, a phase III clinical drug, can target NLRP3 to heal allergic asthma, providing new ideas for the treatment of this disease." (PMID 34413860, 2021). "Using Nlrp3-mutant mice, we found that NLRP3 promotes the inflammatory response and pathogenesis in HDM-induced allergic asthma in an inflammasome-dependent manner." (PMID 34413860, 2021). "However, the mechanism by which NLRP3 affects allergic asthma remains unclear." (PMID 34413860, 2021). "Our data show that eosinophilic airway inflammation in a model of experimental allergic asthma is not mediated by NLRP3." (PMID 41394833, 2025). "The findings of various studies indicate that NLRP3 inhibitors, such as OLT1177® can decrease NLRP3 activity, reduce the release of proinflammatory IL-1β, and alleviate pathophysiological features in mouse models of allergic asthma." (PMID 39364406, 2024). "Therefore, in patients with allergic asthma, the TLR/NF-κB/NLRP3 signaling pathway plays a crucial role in regulating allergic airway epithelial inflammation." (PMID 39364406, 2024).
allergic asthma (continued). "Because the NLRP3 inflammasome was activated by HDM stimulation in vivo, we next investigated whether NLRP3 affected the development of allergic asthma." (PMID 34413860, 2021). "BALF from HDM-treated Nlrp3-/- mice had a comparable number of lymphocytes and IFN-γ secretion to wild-type mice, and NLRP3 impaired only the TH2 subset of helper T cells in HDM-induced allergic asthma." (PMID 34413860, 2021). "In Nlrp3-/-, Il-1b-/-, Asc-/- and Caspase1-/- mice, the inhaled OVA-induced inflammatory response is reduced, indicating that activation of the NLRP3 inflammasome promotes the development of allergic asthma." (PMID 34413860, 2021). "The NLRP3 independent of inflammasomes participated in the pathogenesis of allergic asthma in this model." (PMID 30363922, 2018). "In addition, we found that the activation of NLRP3 helped promote allergic asthma and that this process was independent of inflammasome activation." (PMID 30363922, 2018).
allergic disease (25 papers, 2019 to 2025). An immune response that occurs following re-exposure to an innocuous antigen, and that requires the presence of existing antibodies against that antigen. "To further analyze the potential inflammasome-independent role of NLRP3 in BP allergy, we next sensitized Casp1-deficient animals in addition to C57BL/6 WT and Nlrp3-/- mice." (PMID 38933263, 2024). "This might explain why with HDM-induced models, Nlrp3-deficient mice show similar signs of allergy as their WT counterparts." (PMID 38933263, 2024). "In addition, the knockout of NLRP3 attenuated the level of IL-1β and Caspase-1 cleavage in the asthmatic lung compared with WT asthmatic mice underlying the involvement of the NLRP3 inflammasome in the development of allergic diseases." (PMID 36203607, 2022). "Fueled by the rising global burden of allergic diseases, researchers are increasingly interested in the role of the NLRP3 inflammasome in their development." (PMID 39131161, 2024). "Based on the stronger allergic outcome of the adjuvant-free i.n. sensitization model, we used this procedure to elucidate the role of NLRP3 in BP allergy." (PMID 38933263, 2024). "Some research indicates that several alternative pathways can activate NLRP3 inflammasome-mediated pyroptosis, thereby contributing to the development of allergic diseases." (PMID 39131161, 2024). "Recent research has identified natural small molecules with the potential to inhibit NLRP3 inflammasome activation, which can act as potential treatments for allergic diseases." (PMID 39131161, 2024). "This review has illuminated the critical role of NLRP3 inflammasome-mediated pyroptosis in allergic diseases, delving into the intricate mechanisms by which NLRP3 activation fuels inflammation and exacerbates allergic symptoms." (PMID 39131161, 2024). "Recently, accumulating evidence from human and mouse experiments has demonstrated the critical involvement of the NLRP3 inflammasome, IL-1β, and IL-18 in the development of allergic diseases." (PMID 38277371, 2024). "Mounting evidence from experimental studies suggests NLRP3 plays a critical role in the immune response to allergens, making it a promising therapeutic target for allergic diseases." (PMID 39131161, 2024). "Understanding these diverse NLRP3 activation pathways is crucial for developing novel therapeutic strategies for allergic diseases." (PMID 39131161, 2024). "This interest stems from the potential of the NLRP3 inflammasome as a therapeutic target for allergic diseases, as evidenced by ongoing research on NLRP3 inhibitors." (PMID 39131161, 2024). "It represents a selective and direct small molecule inhibitor of NLRP3, offering potential as a treatment for NLRP3-mediated allergic diseases." (PMID 39131161, 2024). "In summary, the NLRP3 inflammasome can be activated through various mechanisms, pathways, and substances, all of which contribute to the occurrence and development of allergic diseases." (PMID 39131161, 2024). "We will discuss small molecule drugs and natural products targeting NLRP3 as potential therapeutic strategies for allergic diseases." (PMID 39131161, 2024). "Targeting the NLRP3 inflammasome activation pathway or the cleavage process of inflammatory mediators presents a potential therapeutic strategy for allergic diseases." (PMID 39131161, 2024). "As a clinical NLRP3 inflammasome inhibitor, Oridonin holds promise for future applications in the treatment of allergic diseases." (PMID 39131161, 2024). "MCC950 emerges as a promising candidate for the treatment of inflammatory diseases, with its specific inhibition offering a potential therapeutic strategy for allergic diseases involving typical and/or atypical NLRP3 inflammasomes." (PMID 39131161, 2024). "Recent studies in humans and mice strongly suggest a link between the NLRP3 inflammasome, IL-1β, and IL-18, and the development of allergic diseases." (PMID 39131161, 2024).